GALT (galactose-1-phosphate uridylyltransferase)
Description:
Plays an important role in galactose metabolism.
Tractability: Small molecule: a structure with a bound ligand is known. PROTAC: ubiquitination databases record sites on it; its protein half-life has been measured.
Gene: Protein-coding gene on chromosome 9 (34,637,367 to 34,651,754, forward strand). Ensembl gene ENSG00000213930.
Subcellular location (Human Protein Atlas): Cytosol
Pathways (Reactome):
Disease: Defective GALT can cause GALCT
Metabolism: Galactose catabolism
Gene Ontology:
Molecular function: protein binding; UDP-glucose:hexose-1-phosphate uridylyltransferase activity; zinc ion binding
Biological process: galactose metabolic process; UDP-alpha-D-glucose metabolic process; galactose catabolic process via UDP-galactose, Leloir pathway
Cellular component: Golgi apparatus; cytoplasm; cytosol
Genetic constraint (gnomAD): Loss-of-function variants: 43 observed, 59.31 expected, observed/expected ratio (o/e) 0.73, 90% interval 0.57 to 0.94. The upper end of that interval is the gene's LOEUF score, 0.94, which puts it in group 3 of 6, group 1 being the genes least tolerant of losing a copy. Missense variants: 407 observed, 524.39 expected, observed/expected ratio (o/e) 0.78, 90% interval 0.71 to 0.84. Synonymous variants: 154 observed, 192.09 expected, observed/expected ratio (o/e) 0.8, 90% interval 0.7 to 0.92.
Homologues: Orthologues: dog GALT (93% identical), guinea pig GALT (91% identical), rat Galt (89% identical), mouse Galt (87% identical), pig GALT (82% identical), zebrafish galt (67% identical), Drosophila melanogaster Galt (53% identical), Caenorhabditis elegans ZK1058.3 (45% identical), tropical clawed frog galt (44% identical).
Diseases named in the same sentence as GALT in open-access papers:
GALT is named in the same sentence as 65 diseases in open-access papers, as found by Europe PMC text mining. Sharing a sentence is not in itself a finding about the gene and the disease. The quoted sentences say what the papers report.
galactosemia (113 papers, 2006 to 2025). "Classic Galactosemia is a rare inherited metabolic disorder caused by a deficiency in the galactose‐1‐phosphate uridylyltransferase (GALT) enzyme." (PMID 40352451, 2025). "All patients had < 1% GALT enzyme activity (median 0.0 nmol/h/mg of hemoglobin) which is diagnostic for Classic Galactosemia." (PMID 41029344, 2025). "Here, we have found a recurrent mis-sense variant in GALT (p.L195P) in patients 4 and 13; this variant accounts for approximately 2.6% of classic galactosemia alleles." (PMID 40428427, 2025). "In contrast, those with clinical variant galactosemia possess one or more hypomorphic GALT variants resulting in residual enzyme activity ranging from 1% to 10%, at least in some tissues." (PMID 40352451, 2025). "Both studies screened a largely overlapping core panel of disorders, including PKU, MSUD, 3-MCC, MMA, GA-I, IVA, HMG, MCAD, galactosemia due to GALT deficiency, BTD, ASA, and CTLN1." (PMID 40700042, 2025). "Galactosemia due to GALT deficiency, PCD, MCAD, 3-MCC, and PKU had an accumulative incidence of 1:12,111, 1:12,544, 1:14,049, 1:16,725, and 1:19,513, respectively." (PMID 40700042, 2025). "The most common form of galactosemia, known as Classic Galactosemia or Type I Galactosemia, is a result of a severe deficiency in the galactose-1-phosphate uridylyltransferase (GALT) enzyme that occurs in 1/16,000 to 1/60,000 births worldwide." (PMID 41029344, 2025). "We report the case of a now 12‐year‐old male compound heterozygous for a novel GALT null variant and the p.Ser135Leu variant, associated with clinical variant galactosemia." (PMID 40352451, 2025). "The most frequent and well‐studied in this pathway is classic galactosemia (CG) (OMIM 230400) due to pathogenic variants in the GALT gene." (PMID 39953772, 2025). "Purple sweet potato color (PSPC) supplementation has shown promise in addressing complications of classic galactosemia in a GALT‐deficient mouse model." (PMID 39953772, 2025). "Galactosemia is an autosomal recessive disorder that results from deficiency of the enzyme galactose-1-phosphate uridylyltransferase (GALT) that catalyzes the conversion of galactose to glucose." (PMID 40790757, 2025). "The GALT variant S135L is common among galactosemia patients of African, African‐American, Portuguese, and Brazilian ancestry and is associated with cryptic residual GALT activity, at least in some tissues." (PMID 40352451, 2025). "Different inborn errors of metabolism in this pathway are known, the most frequent and well‐studied being Classic Galactosemia (CG) (OMIM 230400) due to pathogenic variants in the GALT gene." (PMID 39953772, 2025). "The most severe manifestation of classic galactosemia is caused by galactose-1-phosphate uridylyltransferase (GALT) deficiency, and this condition can be fatal during infancy if left untreated." (PMID 38778342, 2024). "Based on a successful pilot, a screening algorithm with Gal-1-P as the first-tier screening test, and GALT enzyme activity as the second-tier to identify newborns suspected to be at risk for classical galactosemia has been implemented [1349]." (PMID 38920845, 2024). "In Classic Galactosemia (CG), severe deficiency of GALT (<1% residual activity) fuels several alternative galactose disposal routes." (PMID 38425716, 2024). "Galactosemia is an autosomal recessive hereditary disorder arising from the deficiency of Galactose-1-Phosphate Uridylyltransferase (GALT) gene." (PMID 39095891, 2024). "Classic galactosemia (CG) is the most common and severe form of galactosemia, caused by mutations in the GALT gene encoding the enzyme galactose‐1‐phosphate uridylyltransferase." (PMID 39440457, 2024).
galactosemia (continued). "Classic galactosemia (CG) arises from loss‐of‐function mutations in the Galt gene, which codes for the enzyme galactose‐1‐phosphate uridylyltransferase (GALT), a central component in galactose metabolism." (PMID 38974607, 2024). "Classic galactosemia (CG) is an inborn error of galactose metabolism caused by mutations in the GALT gene." (PMID 39440457, 2024). "Classic galactosemia (CG) (OMIM: 230400) is an autosomal recessive disorder caused by the deficiency of galactose-1-phosphate uridylyltransferase (GALT, EC 2.7.7.12) activity." (PMID 38352271, 2024). "Classical galactosemia (also known as type I galactosemia) is caused by the deficiency of galactose-1-phosphate uridylyltransferase (GALT)." (PMID 38778342, 2024). "Concerning classical galactosemia (GALT deficiency), three cases (namely, D1, K1, and L1) were found to carry five variants in the GALT gene, four of which were unique (the Duarte-2 variant was identified in cases D1 and L1)." (PMID 38090149, 2023). "This variant has already been described in cases with classic galactosemia of Greek origin, where in combination with known GALT mutations it resulted in a typical galactosemia phenotype." (PMID 38090149, 2023). "Human pathogenic coding variations of the galactose-1-phosphate uridylyltransferase (GALT) gene cause classic galactosemia, a recessive disease of galactose metabolism." (PMID 36788839, 2023). "GALT deficiency or classic galactosemia (OMIM 230400) caused by mutations in the GALT gene emerges during the neonatal period and presents with feeding problems, liver dysfunction, lethargy, bleeding diathesis, growth failure, and sepsis." (PMID 38090149, 2023). "c.855G>T (p.K285N) is the second most frequent GALT genetic variant in European patients, accounting for 26–34% of galactosemia alleles." (PMID 38139222, 2023). "Galactosemia type I or classic galactosemia is a rare metabolic disorder occurring in neonates and consisting of a deficiency in galactose-1-phosphate uridylyltransferase (GALT) activity." (PMID 37213895, 2023). "Classical galactosaemia (CG) caused by galactose‐1‐phosphate uridyltransferase (GALT) deficiency occurs secondary to bi‐allelic GALT variants (OMIM#230400), at an incidence of ~1/50 000 live‐births in Caucasians." (PMID 36873086, 2023). "Classic galactosemia (CG) is caused by mutations in the GALT gene, leading to a profound deficiency of galactose-1-phosphate uridylyltransferase (GALT), the central enzyme of galactose metabolism." (PMID 37759536, 2023). "Type 1 galactosemia (OMIM #230400) is caused by deficient activity of the GALT enzyme, which catalyzes the conversion of galactose-1-phosphate and UDP-glucose to UDP-galactose and glucose-1-phosphate (Glc-1-P)." (PMID 38139222, 2023). "When an individual inherits a severe GALT variant (usually associated with classic galactosemia) and the Duarte variant, the clinical presentation is typically asymptomatic and is referred to as Duarte galactosemia." (PMID 34426854, 2022). "Classical galactosemia (CG) is a disorder of galactose metabolism which results from deficiency of the enzyme galactose‐1‐phosphate uridylyl transferase (GALT)." (PMID 36348783, 2022). "Classic Galactosemia is caused by mutations in the GALT gene encoding the enzyme galactose-1 phosphate uridylyltransferase." (PMID 36414970, 2022).
galactosemia (continued). "The major target is, however, galactose-1-phosphate uridyltransferase (GALT) deficiency galactosemia, which is diagnosed by applying a combination of total galactose and GALT enzyme analysis as well as, in certain programs, mutation screening." (PMID 36615667, 2022). "Clinical variant of galactosemia is associated with a low residual GALT activity (usually less than 10–15%) and shows less severe neonatal symptoms and a lower risk of long-term absence or moderate complications if an appropriate diet regimen is started early." (PMID 35883524, 2022). "Classic Galactosemia, also known as Type I Galactosemia, is a result of galactose-1-phosphate uridylyltransferase (GALT) gene mutation, and is the most common form of Galactosemia, occurring in 1/16,000 to 1/60,000 births worldwide." (PMID 35346295, 2022). "Classic Galactosemia (CG) is a devastating inborn error of the metabolism caused by mutations in the GALT gene encoding the enzyme galactose-1 phosphate uridylyltransferase in galactose metabolism." (PMID 35955788, 2022). "Galactose-1-phosphate uridyl transferase (GALT) (c.442C > T [p.Arg148Trp]) mutation was detected in three of galactosemia patients." (PMID 35844336, 2022). "Type 1 galactosemia is due to mutations of the GALT gene mapped on chromosome 9p13 and is the most frequent galactosemia form with a prevalence of about 1: 60,000 live births in the general population, and 1:47,000 in the Caucasian population." (PMID 35883524, 2022). "Classic Galactosemia (CG) is an inherited disease caused by mutations in the GALT gene encoding the enzyme galactose-1 phosphate uridylyltransferase in the galactose metabolic pathway." (PMID 36414970, 2022). "While the clinical variant of galactosemia is linked to 1 to 10% residual GALT activity in erythrocytes and/or the liver, the biochemical variant is linked to 15 to 33% residual GALT activity in erythrocytes." (PMID 36615667, 2022). "Classical galactosemia (CG) (OMIM # 230400) is a disorder of galactose metabolism which results from deficiency of the enzyme galactose‐1‐phosphate uridylyl transferase (GALT), a central enzyme in the highly conserved Leloir pathway of galactose metabolism." (PMID 36348783, 2022). "GALT deficiency results in classic galactosemia, which is a rare, serious, life-threatening condition, in which symptoms most often begin in the second half of the first week of life." (PMID 36615667, 2022). "Classic Galactosemia (CG) is a devastating inborn error of the metabolism caused by deleterious mutations in the gene encoding the enzyme galactose-1-phosphate uridylyltransferase (GALT)." (PMID 35955788, 2022). "Classic galactosemia is caused by pathogenic genetic variants in the GALT gene, which is located on chromosome 9, leading to a severely diminished enzymatic activity." (PMID 33525536, 2021). "Classic galactosemia (OMIM: #230400) is a rare disease affecting people carrying mutations in the gene coding for the enzyme galactose-1-phosphate uridylyltransferase (GALT), catalyzing the third step in the Leloir pathway of galactose metabolism." (PMID 34641605, 2021). "The reported studies illustrate the potential of gene therapy for the treatment of GALT-deficient galactosemia." (PMID 33525536, 2021). "Early in vivo studies on patients with GALT deficiency using [1‐14C]‐galactose demonstrated that individuals with classic galactosemia oxidize up to 8% galactose in 5 hours, whereas in control individuals, 30% to 35% of galactose is oxidized in that duration." (PMID 33977035, 2021). "Classic galactosemia is an inborn error of metabolism associated with mutations that impair the activity and the stability of galactose-1-phosphate uridylyltransferase (GALT), catalyzing the third step in galactose metabolism." (PMID 34641605, 2021). "Type I (classic) galactosemia, galactose 1-phosphate uridylyltransferase (GALT)-deficiency is a hereditary disorder of galactose metabolism." (PMID 33525536, 2021).
galactosemia (continued). "NBS systems for classic galactosemia often contain only GALT activity and Gal-1-P, thus patients with GALM deficiency will be missed." (PMID 34842598, 2021). "Other genes and anatomic abnormalities identified in these African studies included GALT:c.404c>G, a gene associated with galactosemia, and left ventricular hyper-trabeculation (an anatomic defect that can lead to fatal arrhythmias)." (PMID 35003713, 2021). "Since most of the missense mutations affecting GALT are known or predicted to destabilize this protein, a therapy based on pharmacological chaperones has also been suggested for classic galactosemia." (PMID 34641605, 2021). "GALT deficiency causes the most severe galactosemia (type I galactosemia, known as classic galactosemia), which is potentially lethal." (PMID 34842598, 2021). "Approaches specifically aimed in tackling the clinical consequences of galactosemia beyond the neonatal period cover the many aspects of the plethora of signs and symptoms associated with GALT-deficiency." (PMID 33525536, 2021). "In classic galactosemia, GALT enzymatic deficiency causes the accumulationof Gal-1-P, the product of the enzyme galactokinase 1 (GALK1; EC 2.7.1.6)upstream of GALT in the Leloir pathway." (PMID 33724769, 2021). "The high occurrence of missense mutations (>60%) and experimental evidence of misfolding and decreased stability of GALT variants makes classic galactosemia highly amenable to this therapeutic approach." (PMID 33525536, 2021). "We used this last model as a starting point to model the structures of all the known galactosemia-associated mutants of the GALT enzyme and to perform a deep investigation of the effects of the mutations on the structure, function, and stability of the enzyme." (PMID 34641485, 2021). "The diagnosis of galactosemia was confirmed via Sanger sequencing—the patient was homozygous for the pathogenic GALT variant NM_000155.3(GALT):c.329−2A>C." (PMID 33113773, 2020). "It has previously been demonstrated that in fibroblasts derived from GALT-deficient galactosemia patients and GALT-deficient yeast, the cytostatic effect of extracellular galactose can be reduced by overexpressing UGP." (PMID 32188137, 2020). "These cells are of considerable interest because their inability to grow when galactose is the only carbon source is also a characteristic of cells from GALT-deficient galactosemia patients in which elevated cellular Gal1P levels are thought to be cytotoxic." (PMID 32188137, 2020). "We selected GALT in our studies as its complete deficiency in human causes classic galactosemia, an inborn error of metabolism." (PMID 32028604, 2020). "This is because such changes are well-documented in clinical studies of patients with GALT-deficiency classic galactosemia." (PMID 32028604, 2020). "The galactosemia diagnosis was confirmed via the Sanger sequencing method—a novel, likely pathogenic, homozygous variant in the GALT gene NM_000155.4:c.305T>C (p.Leu102Pro) was identified." (PMID 33113773, 2020). "Galactosemia is caused by galactose-1-phosphate uridylyltransferase (GALT) deficiency, resulting in the toxic accumulation of galactose metabolites which need to be countered with an appropriate diet." (PMID 32971894, 2020). "Classic galactosemia is an autosomal recessive disorder caused by deleterious variants in the galactose‐1‐phosphate uridylyltransferase (GALT) gene." (PMID 31392114, 2019). "Classical galactosemia (CG) is due to a severe deficiency of the galactose-1-phosphate uridyl-transferase (GALT), the main enzyme of galactose metabolism." (PMID 30808388, 2019). "This is an important gap in galactosemia research that needs to be addressed since the effect of variants on GALT function can vary in severity." (PMID 31392114, 2019).